PDXP (pyridoxal phosphatase)
Description:
Functions as a pyridoxal phosphate (PLP) phosphatase, which also catalyzes the dephosphorylation of pyridoxine 5'-phosphate (PNP) and pyridoxamine 5'-phosphate (PMP), with order of substrate preference PLP > PNP > PMP and therefore plays a role in vitamin B6 metabolism. Also functions as a protein serine phosphatase that specifically dephosphorylates 'Ser-3' in proteins of the actin-depolymerizing factor (ADF)/cofilin family like CFL1 and DSTN. Thereby, regulates cofilin-dependent actin cytoskeleton reorganization, being required for normal progress through mitosis and normal cytokinesis. Does not dephosphorylate phosphothreonines in LIMK1. Does not dephosphorylate peptides containing phosphotyrosine.
Synonyms: CIN; PLP; dJ37E16.5; FLJ32703
Tractability: Small molecule: a structure with a bound ligand is known; it has a high-quality binding pocket. Antibody: UniProt places it where antibodies can reach, with high confidence; its Gene Ontology location is reachable by antibodies, with high confidence. PROTAC: ubiquitination databases record sites on it; its protein half-life has been measured.
Gene: Protein-coding gene on chromosome 22 (37,658,723 to 37,666,932, forward strand). Ensembl gene ENSG00000241360.
Subcellular location: Cytoplasm, cytosol; Cytoplasm, cytoskeleton; Cell projection, ruffle membrane; Cell projection, lamellipodium membrane; Cell membrane
Gene Ontology:
Molecular function: heat shock protein binding; phosphoprotein phosphatase activity; protein binding; protein serine/threonine phosphatase activity; pyridoxal phosphatase activity; magnesium ion binding; phosphatase activity; protein homodimerization activity
Biological process: actin rod assembly; cellular response to ATP; dephosphorylation; positive regulation of actin filament depolymerization; protein dephosphorylation; pyridoxal phosphate catabolic process; regulation of cytokinesis; regulation of mitotic nuclear division; regulation of modification of postsynaptic structure; vitamin B6 catabolic process
Cellular component: actin cytoskeleton; cleavage furrow; contractile ring; cytosol; lamellipodium; midbody; plasma membrane; ruffle membrane; cell-cell junction; cytoskeleton; glutamatergic synapse; lamellipodium membrane; postsynapse
Genetic constraint (gnomAD): Loss-of-function variants: 15 observed, 10.35 expected, observed/expected ratio (o/e) 1.45, 90% interval 0.95 to 1.91. The synonymous counts are far from expectation, so gnomAD's model fits this gene poorly and the ratio says little. Missense variants: 413 observed, 322.15 expected, observed/expected ratio (o/e) 1.28, 90% interval 1.18 to 1.39. Synonymous variants: 233 observed, 157.03 expected, observed/expected ratio (o/e) 1.48, 90% interval 1.33 to 1.65.
Homologues: Orthologues: chimpanzee PDXP (99% identical), dog PDXP (95% identical), pig PDXP (94% identical), rat Pdxp (92% identical), mouse Pdxp (91% identical), guinea pig PDXP (90% identical), zebrafish pdxp (54% identical), Drosophila melanogaster CG5567 (35% identical), Caenorhabditis elegans pgph-2 (32% identical), Caenorhabditis elegans pgph-3 (32% identical), Caenorhabditis elegans pgph-1 (32% identical), Drosophila melanogaster CG5577 (32% identical), and 7 more. Paralogues in human: PGP (46% identical), LHPP (26% identical), HDHD2 (26% identical).
Diseases named in the same sentence as PDXP in open-access papers:
PDXP is named in the same sentence as 35 diseases in open-access papers, as found by Europe PMC text mining. Sharing a sentence is not in itself a finding about the gene and the disease. The quoted sentences say what the papers report.
glioma (3 papers, 2018 to 2021). A benign or malignant brain and spinal cord tumor that arises from glial cells (astrocytes, oligodendrocytes, ependymal cells). "Previous studies reported that monoallelic PDXP (Pyridoxal phosphate phosphatase) loss frequently occurred in gliomas and the occurrence rate increased along with glioma grades." (PMID 34912844, 2021). "The phosphatase chronophin (CIN/PDXP) has been shown to be an important regulator of glioma cell migration and invasion." (PMID 29724193, 2018). "This motivated us to examine the role of the cofilin phosphatase chronophin (CIN/PDXP) in glioma cells cultured under non-adherent, serum-free conditions." (PMID 29724193, 2018).
autoimmune Addison's disease (1 paper, 2004). "In addition, one of 47 (2.1%) patients with type 1 diabetes (three of 72 (4.1%) patients with autoimmune Addison's disease or APS and two of 47 (4.5%) MS patients had autoantibodies against PDXP (P=0.008 when comparing all four control groups with all cancer patients)." (PMID 15452547, 2004).
autoimmune disease (1 paper, 2004). A disorder resulting from loss of function or tissue destruction of an organ or multiple organs, arising from humoral or cellular immune responses of the individual to their own tissue constituents. "In addition, 2–4% of patients with different autoimmune diseases had autoantibodies against pyridoxal phosphatase." (PMID 15452547, 2004).
Cerebral ischemia (1 paper, 2018). Restriction of arterial blood supply to the brain associated with insufficient oxygenation to support the metabolic requirements of the tissue. "PDXP levels increase in brain following cerebral ischemia, and decrease after the administration of neuroprotective free radical scavengers, such as ferulic acid." (PMID 29784938, 2018).
ischemia (1 paper, 2018). A hypoperfusion of the BLOOD through an organ or tissue caused by a PATHOLOGIC CONSTRICTION or obstruction of its BLOOD VESSELS, or an absence of BLOOD CIRCULATION. "In our study, we reported high levels of PDXP in CSF early after ischemia, but we were not able to detect changes in brain levels neither in plasma at the studied time-point." (PMID 29784938, 2018).
lung carcinoma (1 paper, 2004). "This study identified PDXP as a novel autoantigen associated with various types of cancer, including lung cancer." (PMID 15452547, 2004). "Onconeuronal antibodies (anti-Hu) were detected in five of the anti-PDXP positive sera from the patients with lung cancer using immunofluorescence and immunoblot." (PMID 15452547, 2004). "Sera contained antibodies against pyridoxal phosphatase in 22 of 243 (9.1%) patients with lung cancer and eight of 113 (7.1%) with other forms of cancer vs two of 88 (2.3%) healthy control subjects." (PMID 15452547, 2004). "In total, 9% of patients with lung cancer and 7% of patients with other types of cancer revealed reactivity against PDXP vs 2% among healthy controls." (PMID 15452547, 2004). "Among the patients with sera containing PDXP antibodies detected by RIA, five of 15 (33%) patients with lung cancer and three of eight (38%) patients with various types of cancer recognised PDXP by Western blot." (PMID 15452547, 2004). "Five of the lung cancer patients positive for anti-PDXP also had circulating Hu-antibodies but not clinically evident PND." (PMID 15452547, 2004).
rheumatoid arthritis (1 paper, 2005). A chronic, systemic autoimmune disorder characterized by inflammation in the synovial membranes and articular surfaces. "The low plasma pyridoxal 5'-phosphate level in patients with rheumatoid arthritis may also be attributed to elevated pyridoxal phosphatase activity during inflammation." (PMID 16277678, 2005).
Stroke (1 paper, 2018). Sudden impairment of blood flow to a part of the brain due to occlusion or rupture of an artery to the brain. "It remains to be tested whether PDXP increases in the ischemic brain at later stages after ischemia, which would potentially serve as a therapeutic target to mediate the mechanisms of stroke-related tissue injury." (PMID 29784938, 2018).
cancer (10 papers, 2004 to 2023). A tumor composed of atypical neoplastic, often pleomorphic cells that invade other tissues. "Future studies on more well-defined patient materials should elucidate the sensitivity and specificity of the association between antibodies against PDXP and cancer." (PMID 15452547, 2004). "suggest that in cancer, doxorubicin‐triggered RhoA activation is associated with phospho‐cofilin dephosphorylation due to PDXP activation 48, and LPS was reported to dephosphorylate cofilin via PDXP induction." (PMID 29363851, 2018). "In conclusion, PDXP is a novel autoantigen associated with cancer." (PMID 15452547, 2004). "Autoantibodies against several different proteins are frequent in cancer patients, and most appear in a wide variety of types of cancer, similar to our findings of anti-PDXP." (PMID 15452547, 2004). "We found high expression in the central nervous system but also in a number of cancer cell lines, which could explain why PDXP becomes an autoantigen in patients with cancer." (PMID 15452547, 2004). "Our findings therefore indicate that PDXP is associated with cancer and not with PND, but the latter association cannot be ruled out." (PMID 15452547, 2004). "The Multiple Tissue Expression Array revealed that some cancer cell lines express PDXP." (PMID 15452547, 2004). "PDXP had never been associated with miR-1281 in other cancers, and the tumorigenic functions of miR-1281 in GBMs may rely on PDXP." (PMID 34912844, 2021). "In addition, PDXP regulated active vitamin B6 levels and transcriptomic features of GBM cell lines cultured under non-adherent, serum-free conditions, indicating a potential role of PDXP in tumor metabolism and cancer stem cells." (PMID 34912844, 2021). "Hence, autoantibodies against pyridoxal phosphatase correlate with cancer but not necessarily with the subset of patients with paraneoplastic neurological disorders although serum from such a patient was used to screen the cDNA library." (PMID 15452547, 2004).
tumor (8 papers, 2004 to 2023). "In summary, circLRRC7 may be a tumor suppressor that associated with miR-1281 and PDXP expression in GBM, which may provide novel therapeutic targets for GBM treatment." (PMID 34912844, 2021). "In this study, by systematic analysis of existing databases, we detected circLRRC7 as a tumor suppressor and proposed miR-1281 and PDXP as potential downstream genes of circLRRC7 in GBM pathogenesis." (PMID 34912844, 2021). "One theory is that some tumours express elevated levels of PDXP to overcome the suppressive effect of vitamin B6." (PMID 15452547, 2004). "Analysis showed that miR-1281 might be a downstream target of circLRRC7 and that PDXP, a protein that participates in tumor metabolism, was the direct target of miR-1281." (PMID 37415736, 2023). "Instead, prolonged HIF1 stabilization, as would occur following HIF1 overexpression or during exposure to chronic hypoxia within the tumor microenvironment, may be required for robust upregulation of PDXP in T cells." (PMID 35251031, 2022). "The results showed that PDXP had a lower expression in tumor relative to normal tissues." (PMID 34912844, 2021). "One might speculate increased expression of PDXP degrade PLP, thereby facilitating tumour growth, but this could also lead to an enhanced immune response against the tumour." (PMID 15452547, 2004).
brain disorder (1 paper, 2024). A disease affecting the brain or part of the brain. "The experiments showed that a molecule called 7,8-dihydroxyflavone – which was previously found to improve memory and learning in laboratory animals with brain disorders – binds to pyridoxal phosphatase and inhibits its activity." (PMID 38856179, 2024). "The identification of 7,8-DHF as a PDXP inhibitor reported here indicates that this flavone may modulate vitamin B6-dependent processes and suggests that PDXP could be explored as a pharmacological entry point into brain disorders." (PMID 38856179, 2024).
PDXP also shares sentences with these, for which no sentence is quoted: epilepsy (3 papers); neurodevelopmental disorder (3); glioblastoma (2); infection (2); psychiatric disorder (2); Seizure (2); Adult onset (1); Alzheimer disease (1); autism spectrum disorder (1); breast carcinoma (1); colon cancer (1); colorectal cancer (1); depression (1); developmental epileptic encephalopathies (1); intellectual disabilities (1); kidney cancer (1); lung adenocarcinoma (1); neurodegenerative disease (1); neurological disorders (1); orofacial clefting (1); schizophrenia (1); status epilepticus (1); type 1 diabetes (1); uremia (1).